NRAV (negative regulator of antiviral response)
Synonyms: DYNLL1-AS1; DYNLL1AS1
Gene: Long non-coding RNA gene on chromosome 12 (120,488,079 to 120,495,954, reverse strand). Ensembl gene ENSG00000248008.
Diseases named in the same sentence as NRAV in open-access papers:
NRAV is named in the same sentence as 15 diseases in open-access papers, as found by Europe PMC text mining. Sharing a sentence is not in itself a finding about the gene and the disease. The quoted sentences say what the papers report.
viral infection (4 papers, 2017 to 2025). "For example, a lncRNA named negative regulator of antiviral response (NRAV) acts as a key regulator of host defense against viral infection, which negatively regulates the initial transcription of multiple ISGs during IAV infection." (PMID 34054851, 2021). "For instance, lncRNA-CMPK2 and -NRAV have been found to negatively regulate interferon response, which is an important component of innate immune system against viral infections." (PMID 29033949, 2017). "Our previous study has identified lncRNA NRAV as a key regulator of initial transcription of multiple critical ISGs, indicating the functional involvement of lncRNAs in innate immunity against viral infection." (PMID 34054851, 2021). "lncRNA NEAT, 7SL, NRAV, lnc-ISG20, and CCR5AS have been reported to regulate the innate immune responses to virus infection." (PMID 32153544, 2020).
endometrial cancer (3 papers, 2021 to 2023). Primary or metastatic malignant neoplasm involving the endometrium (mucous membrane that lines the endometrial cavity). "However, LINC02014 and NRAV were significantly downregulated in endometrial carcinoma (p < 0.05)." (PMID 35957871, 2022). "Previous bioinformatic analysis showed lncRNA NRAV involved in HCC, Endometrial cancer, and lower-grade glioma." (PMID 36845390, 2023).
hepatocellular carcinoma (3 papers, 2021 to 2024). A malignant tumor that arises from hepatocytes. "Higher expression of NRAV was associated with advanced clinical stage, poor prognosis and immunologic characteristics in hepatocellular carcinoma patients." (PMID 34650600, 2021). "The subcellular localization of NRAV in hepatoma cells was detected by nuclear and cytoplasmic separation experiments, and it was found that NRAV was located not only in the cytoplasm but also in the nucleus." (PMID 38637761, 2024). "Some studies have shown that NRAV play a role in immune checkpoints in hepatocellular carcinoma (HCC), while other studies have identified ferroptosis as a possible mechanism." (PMID 38560576, 2024).
glioma (2 papers, 2022 to 2023). A benign or malignant brain and spinal cord tumor that arises from glial cells (astrocytes, oligodendrocytes, ependymal cells). "Among the prognosis-related lncRNAs in HCC, SNHG3, SNHG4, and NRAV have been reported to function in bladder cancer, non-small cell lung cancer, osteosarcoma, colorectal cancer, breast cancer, gastric cancer, and glioma through interactive molecular pathway studies." (PMID 35734590, 2022).
latent infection (1 paper, 2023). "While the expression of the transcription-associated lncRNAs, RP11-255C15.3 and CTD-3222D19.12, showed a downregulation after PMA stimulation, the expression of C21orf91-OT1 and NRAV were either unchanged or increased, respectively, compared to latent infection." (PMID 38038477, 2023).
liver cancer (1 paper, 2025). An epithelial or non-epithelial malignant neoplasm that arises from the liver. "Additionally, elevated levels of NRAV expression are associated with poor prognosis in liver cancer patients, and in vitro studies indicate that knockdown of NRAV markedly inhibits the proliferation and migration of liver cancer cells." (PMID 40309008, 2025).
tumor (9 papers, 2021 to 2024). "Pyroptosis, a novel form of programmed inflammatory cell death characterized by necrotic morphologies such as plasma membrane rupture, plays a crucial role in tumor development, therefore, we investigated the association between NRAV expression and pyroptosis-related molecules." (PMID 38560576, 2024). "Our findings suggest that NRAV is a promising biomarker that plays an essential role in the tumor progression of patients with HCC,therefore, NRAV could be a foundation for the development of targeted therapeutic strategies." (PMID 38560576, 2024). "By incorporating the analysis of NRAV’s expression and prognostic significance with an in vitro functionality investigation, we can deduce potential mechanisms elucidating the interaction between NRAV and tumor immunity, thereby highlighting NRAV’s potential role in HCC and other malignancies." (PMID 38560576, 2024). "In this study, NRAV expression was abnormally high in different types of tumors, but low in KICH tumor tissues based on the TCGA database." (PMID 38560576, 2024). "The expression patterns showed that AL031985.3, NRAV, WAC-AS1, AC026412.3, and AC099850.4 were expressed more in the tumor tissues than normal tissues." (PMID 36980686, 2023). "A total of six lncRNAs, including AC099850.4, NRAV, AL031985.3, PRRT3-AS1, AL365203.2, and LINC01224, were highly expressed in tumor tissues, based on TCGA cohort analysis." (PMID 35845962, 2022). "PIK3CD-AS2, AC092171.2, NRAV, ZFPM2-AS1, and CASC19 were risk factors in the m7GRLSig model; the expression of AC092171.2, NRAV, and ZFPM2-AS1 was significantly higher in tumor tissues in the TCGA cohort." (PMID 36661684, 2022). "The five m5C-related lncRNAs, which were NRAV, AL031985.3, MKLN1-AS, ELFN1-AS1, and AL928654.1, were highly expressed in tumor tissues by bioinformatics analysis." (PMID 36339006, 2022). "Nevertheless, the specific functions of ELN-AS1, AC103563.7, AF131215.5, LINC01871, AC08417.1, NRAV, AL049539.1, POC1B-AS1, AC108134.4, and AC019080.5 in the tumor microenvironment remain unknown." (PMID 34925511, 2021).
cancer (7 papers, 2016 to 2024). A tumor composed of atypical neoplastic, often pleomorphic cells that invade other tissues. "We shed light on the potential mechanisms underlying NRAV’s involvement in cancer pathogenesis and validated the expression and function of NRAV in HCC cells both in vitro and in vivo." (PMID 38560576, 2024). "Overall, our findings reveal the complex mechanisms by which NRAV contributes to cancer pathogenesis and progression." (PMID 38560576, 2024). "In conclusion, our study provides significant new insights into the role of NRAV in cancer development and progression." (PMID 38560576, 2024). "The results indicated that NRAV was upregulated in various cancers, including liver hepatocellular carcinoma (LIHC)." (PMID 35436415, 2022). "In this study, many lncRNAs in the risk model, such as ZFPM2-AS1, NRAV, LUCAT1, MKLN1-AS, and LINC01224, were found to exert vital roles in regulating and participating in the progression of different cancers." (PMID 35712653, 2022). "Our study demonstrates a positive association between NRAV and various immune cell types, including B cells, CD4+ T cells, CD8+ T cells, neutrophils, macrophages, and DC cells, in multiple cancer types such as KIRC, LGG, PRAD, LIHC, USC, GBMLGG, KICH, and DLBC." (PMID 38560576, 2024).
infection (3 papers, 2018 to 2022). The state of being infected such as from the introduction of a foreign agent such as serum, vaccine, antigenic substance or organism. "The level of NRAV was markedly reduced following infection with influenza virus and a number of other viruses in several cell lines." (PMID 29503633, 2018). "Both NRAV-overexpressed cells and the control group were infected by RSV (multiplicity of infection [MOI] = 3), and cell lysates were harvested at indicated time points to evaluate RSV replication by virus plaque assay, immunoblotting, and qRT-PCR." (PMID 32102886, 2020). "This repressive role of EGOT resembles what has been described for the lncRNAs NRIR and NRAV, negative regulators of the IFN pathway which are induced by IFN or infection." (PMID 29503633, 2018).
NRAV also shares sentences with these, for which no sentence is quoted: bladder cancer (1 paper); breast carcinoma (1); colorectal cancer (1); gastric cancer (1); non-small cell lung carcinoma (1); osteosarcoma (1).